SPC25 (SPC25 component of NDC80 kinetochore complex)
Diseases named in the same sentence as SPC25 in open-access papers (continued):
Sharing a sentence is not in itself a finding about the gene and the disease.
cancer (18 papers, 2018 to 2025). A tumor composed of atypical neoplastic, often pleomorphic cells that invade other tissues. "Recent investigations have unveiled a noteworthy association between SPC25 dysregulation and carcinogenic processes, as well as malignant phenotypes in certain cancers." (PMID 38605119, 2024). "We found that SPC25 was significantly associated with prognosis, mutation, and immunity in pan-cancer." (PMID 38605119, 2024). "Previous studies have reported that dysregulated SPC25 expression is associated with the oncogenic process and malignant phenotypes of several cancers." (PMID 32742802, 2020). "A recent study reported that SPC25 is up-regulated in lung cancer and is associated with carcinogenesis, cancer cell growth, and metastasis." (PMID 31400751, 2019). "Given these associations, SPC25 could serve as a reliable biomarker for early detection of aggressive cancers, providing clinicians with valuable information to guide treatment strategies." (PMID 40400636, 2025). "High SPC25 expression was associated with patient age (P = 0.025), pathological stage (P = 0.004), histologic grade (P < 0.0001), survival status (P = 0.00029), and family history of cancer (P = 0.01)." (PMID 32742802, 2020). "Its dysregulation in various cancers has positioned SPC25 as a promising candidate for both biomarker development and targeted therapy." (PMID 40400636, 2025). "This section will review the current knowledge regarding these aspects of SPC25, with a focus on its contribution to cancer progression and its potential as a therapeutic target." (PMID 40400636, 2025). "The overexpression of SPC25 in cancer cells enhances cell cycle progression, particularly through its involvement in the G2/M transition." (PMID 40400636, 2025). "Despite these advances, a comprehensive understanding of SPC25’s molecular mechanisms and clinical implications in cancer remains incomplete." (PMID 40400636, 2025). "We conclude by exploring future research directions, emphasizing the need for in-depth studies to unravel the precise molecular functions of SPC25 and its therapeutic potential in cancer treatment." (PMID 40400636, 2025). "In this section, we explore the potential of SPC25 as a biomarker for early diagnosis and prognosis, as well as its value as a therapeutic target in cancer treatment." (PMID 40400636, 2025). "Dysregulation of these mechanisms can lead to SPC25 overexpression or malfunction, which contributes to cancer progression." (PMID 40400636, 2025). "The growing body of evidence highlighting the role of SPC25 in cancer progression has brought this protein into the spotlight as both a potential biomarker and therapeutic target." (PMID 40400636, 2025). "The emerging evidence underscores SPC25’s multifaceted role in cancer biology, offering novel insights into its clinical applications." (PMID 40400636, 2025). "SPC25 not only contributes to chromosomal stability and cell division but also interacts with various critical signaling pathways involved in cancer cell proliferation, survival, and metastasis." (PMID 40400636, 2025). "While considerable progress has been made in understanding the role of SPC25 in various cancers, several limitations in current studies hinder a comprehensive understanding of its function and therapeutic potential." (PMID 40400636, 2025). "While significant progress has been made in understanding the role of SPC25 in cancer, substantial challenges remain in translating these findings into clinical applications." (PMID 40400636, 2025). "One of the primary limitations of existing research is the relatively narrow range of cancer types in which SPC25 expression and function have been investigated." (PMID 40400636, 2025).
cancer (continued). "Further studies are needed to identify the specific transcription factors or regulatory elements that control SPC25 expression in different cancer types, as well as how these pathways integrate with the cellular environment." (PMID 40400636, 2025). "Understanding these regulatory processes in greater detail will offer valuable insights into the therapeutic potential of targeting SPC25 in cancer." (PMID 40400636, 2025). "Future studies should focus on expanding the range of cancers examined to provide a more holistic view of SPC25’s role in tumorigenesis and its potential as a target in diverse cancer types." (PMID 40400636, 2025). "This review aims to provide a detailed examination of the current knowledge regarding SPC25 in cancer biology." (PMID 40400636, 2025). "The expansion of cancer type studies, in-depth mechanistic research, and the development of specific inhibitors are all critical for advancing our understanding of SPC25 as a biomarker and therapeutic target." (PMID 40400636, 2025). "Future studies should broaden the scope of cancers examined for SPC25 expression and its clinical significance." (PMID 40400636, 2025). "These interactions are essential for maintaining genomic stability, and any disruption of the cell cycle-dependent regulation of SPC25 can contribute to cancer progression." (PMID 40400636, 2025). "The functional significance of SPC25 in regulating mitosis, chromosomal stability, and cell proliferation presents a compelling rationale for its targeting in cancer therapy." (PMID 40400636, 2025). "This ability to overcome chemotherapy-induced cell death highlights SPC25 as a potential target for overcoming therapy resistance in cancer treatment." (PMID 40400636, 2025). "Beyond its role in mitosis, SPC25 also contributes to the progression of cancer by influencing various cellular processes such as proliferation, migration, and invasion." (PMID 40400636, 2025). "The study explores the potential of SPC25 as a pan-cancer prognostic and immunotherapy marker, providing new evidence for cancer treatment." (PMID 40400636, 2025). "The results showed that Ferroptosis-related genes such as SLC3A2, HSF1, and SLC7A11 were significantly positively correlated with SPC25 in pan-cancer." (PMID 38605119, 2024). "Our findings suggested that SPC25 generally correlated with many important pathways in cancer formation." (PMID 38605119, 2024). "In some cancer types, SPC25 expression was also markedly correlated with the TMB, MSI, and clinical characteristics." (PMID 38605119, 2024). "Toward this, we performed intersection analysis on the top 200 genes having highest correlation with NDC80 complex components - NDC80, NUFS, SPC24, and SPC25 respectively at the pan-cancer level, and identified 109 overlapping genes." (PMID 39513104, 2024). "In order to preliminarily understand the expression pattern of SPC25 in human cancer, we used the TIMER online tool for analysis." (PMID 38217547, 2024). "In light of this evidence, our focus gravitates toward the mechanisms underpinning SPC25's involvement in multiple tumors, delving deeper at the pan-cancer level." (PMID 38605119, 2024). "We observed markedly elevated gene levels of SPC25 in the majority of tumors, with some cancers demonstrating distinct prognostic implications." (PMID 38605119, 2024). "This study comprehensively explored the potential value of SPC25 as a prognostic and immunotherapeutic marker for pan-cancer, providing new direction and evidence for cancer therapy." (PMID 38605119, 2024). "Data from the UCSC Xena, TIMER2.0, and TCGA were analyzed to investigate the overall differential expression of SPC25 across multiple cancer types." (PMID 38605119, 2024). "Through an exhaustive examination, our research illuminated the prognostic and potential immunotherapeutic significance of SPC25 in the context of pan-carcinoma." (PMID 38605119, 2024).
cancer (continued). "Other biological function experiments indicated that HCC cancer cells with SPC25 overexpression exerted accelerated proliferation, improved migration and invasion, and promoted resistance to chemotherapy, thus reflecting an enhanced stemness phenotype 35." (PMID 36147467, 2022). "Our in vitro and in vivo studies also demonstrated that cancer cells with SPC25 overexpression were more proliferative and prone to metastasis, further confirming that SPC25 facilitated the progression of HCC." (PMID 36147467, 2022). "Reports showed that elevated expression of SPC25 can increase cancer stem cell (CSC) properties and predict poor prognosis." (PMID 36052378, 2022). "SPC25 is upregulated in lung adenocarcinoma, and plays roles in carcinogenesis, cancer cell proliferation, and metastasis." (PMID 35967419, 2022). "SPC25 was further shown as a prominent molecule, which markedly suppressed cancer stemness and attenuated CR after silencing." (PMID 33238517, 2020). "According to UALCAN, SPC25 mRNA expression was notably higher in most human cancer than in the corresponding normal tissue." (PMID 33408271, 2020). "Recently, SPC25 has been found to participate in numerous malignant phenotypes, including proliferation, survival, stemness, and metastasis in various cancers." (PMID 33238517, 2020). "The expression of SPC25 was related to age, pathological stage, histologic grade, survival status, and family history of cancer." (PMID 32742802, 2020). "We identified a novel biological process (mitotic cell division) and demonstrated a hub gene (SPC25) that significantly contributed to cancer stemness and CR." (PMID 33238517, 2020). "Co-expression of both mCherry and nGFP made the SPC25+ cancer cells appear to be yellow fluorescent, and thus allow separation of them from SPC25- cancer cells by flow cytometry." (PMID 30408771, 2018). "In this approach, all cancer cells were labeled with a red fluorescent protein, mCherry, but only those SPC25+ cells were co-labeled with a nGFP to be expressing also green fluorescent." (PMID 30408771, 2018). "In this section, we discuss the limitations of current research and outline future research directions that could help address these challenges and further elucidate the role of SPC25 in cancer." (PMID 40400636, 2025). "These antibodies could inhibit SPC25’s interaction with other mitotic machinery components or block its binding to microtubules, ultimately leading to impaired mitosis and cancer cell death." (PMID 40400636, 2025). "Given its elevated expression in blood samples from cancer patients, SPC25 could potentially be detected in the circulation, offering a promising tool for monitoring disease progression, recurrence, and response to therapy." (PMID 40400636, 2025). "However, cancer cells often develop resistance to these therapies through various mechanisms, including the dysregulation of mitotic regulators like SPC25." (PMID 40400636, 2025). "Given its central role in maintaining kinetochore-microtubule attachment during cell division, disrupting SPC25 function could lead to mitotic errors, cell cycle arrest, and apoptosis in rapidly proliferating cancer cells." (PMID 40400636, 2025). "By consolidating existing evidence, this article seeks to bridge the gap between basic research and clinical applications, offering novel insights into the role of SPC25 in cancer and its implications for the development of innovative diagnostic and therapeutic strategies." (PMID 40400636, 2025). "Additionally, SPC25’s role in stabilizing the kinetochore-microtubule interface offers potential advantages in targeting mitotic progression, particularly in cancers where microtubule dynamics are disrupted by chemotherapy agents." (PMID 40400636, 2025).
cancer (continued). "Cancer cells with elevated SPC25 levels may be better equipped to repair DNA damage induced by chemotherapy, allowing them to survive and proliferate despite treatment." (PMID 40400636, 2025). "Cancer cells often develop resistance to chemotherapy, targeted therapies, and immunotherapies, and SPC25 may play a role in this process." (PMID 40400636, 2025). "Therefore, we further studied the relationship between SPC25 expression and immune infiltration analysis in pan-cancer." (PMID 38605119, 2024). "Data concerning the relationship between SPC25 and cancer development remain scarce." (PMID 38605119, 2024). "We found that SPC25 is a novel biomarker for a variety of cancers." (PMID 38605119, 2024). "Single-gene GSEA was used to identify relevant pathways affected by SPC25 expression in pan-cancer." (PMID 38605119, 2024). "This intimates that SPC25 could function as a potential regulatory target in the immunotherapy of these cancers and suggests its involvement in inducing immune cell recruitment is far from trivial." (PMID 38605119, 2024). "In addition, SPC25 is enriched in cancer stem cells (CSCs), and is required for PrC cell proliferation." (PMID 35967419, 2022). "The silencing of SPC25 increased cisplatin sensitivity and reduced cancer stemness property." (PMID 33238517, 2020). "Given the role of SPC25 in stabilizing the kinetochore-microtubule complex, small molecules targeting SPC25 could potentially mimic these effects, leading to mitotic catastrophe in cancer cells." (PMID 40400636, 2025). "The Kaplan-Meier curve and log-rank test analysis revealed that increased NDC80, NUF2, SPC24, and SPC25 mRNA levels were all significantly associated with the overall survival (OS), disease-free survival (DFS), disease-free interval (DFI), and progression-free interval (PFI) of pan-cancer samples." (PMID 39513104, 2024). "Thus, this combination regimen of celastrol and SPC25-silencing may be further developed for the treatment of refractory cancers." (PMID 33238517, 2020). "Additionally, SPC25 is involved in carcinogenesis, cancer cell growth, and metastasis." (PMID 32742802, 2020). "However, the prognostic and immunotherapeutic value of SPC25 in pan-cancer remains unclear." (PMID 38605119, 2024). "In Cuproptosis-related genes, SPC25 was positively correlated with GCSH, CDKN2A, PDHB, PDHA1, DLAT, DLD, and SLC31A1 of pan-cancer." (PMID 38605119, 2024). "Post-translational modification targeting is also one of the directions, but no studies have shown that SPC25-specific post-translational modifications (phosphorylation, ubiquitination) exist in cancer cells and can be used as targets." (PMID 40400636, 2025). "Emerging evidence suggests that SPC25 is not merely a passive player in cell division but also participates in oncogenic signaling pathways, making it an intriguing target for cancer research." (PMID 40400636, 2025). "The lack of comprehensive data across different cancer types restricts the generalizability of SPC25 as a universal biomarker or therapeutic target." (PMID 40400636, 2025). "Recent studies have shown that abnormalities in ferroptosis are commonly present in various cancers, but there have been no reports on the relationship between SPC25 and ferroptosis." (PMID 38217547, 2024). "The cancer patients with higher expression of NDC80, NUF2, SPC24, and SPC25 were predicted to have worse OS, DFS, DFI, and PFI, which suggested that NDC80 complex components may be potential prognostic indicator molecules in pan-cancer." (PMID 39513104, 2024). "For most cancers, SPC25 expression exhibited no significant discrepancies based on clinical stage, age, or sex." (PMID 38605119, 2024). "Thence, we further explored the relationship of SPC25 with TMB and MSI in the pan-cancer cohort." (PMID 38605119, 2024).
cancer (continued). "Targeting SPC25 could therefore offer a more specific approach to modulating mitotic functions compared to other NDC80 components, making it a promising candidate for therapeutic intervention in cancer treatment." (PMID 40400636, 2025). "Furthermore, SPC25’s role in maintaining genomic stability and promoting cell proliferation may help establish a TME conducive to the survival and expansion of cancer cells." (PMID 40400636, 2025).
infection (1 paper, 2023). The state of being infected such as from the introduction of a foreign agent such as serum, vaccine, antigenic substance or organism. "Following hepatic portal perfusion, we only recovered about 50% of RNAi-treated worms initially infected, suggesting RNAi-SPC25 parasites cannot maintain infection in vivo." (PMID 36936776, 2023). "The statistical results of the number of oviposition showed that after infection with RNAi-SPC25 worms, the number of eggs in the mouse liver was reduced by 62.02% compared with the control group." (PMID 36936776, 2023).
SPC25 also shares sentences with these, for which no sentence is quoted: bladder cancer (3 papers); anaplastic large cell lymphoma (1); cervical cancer (1); cholangiocarcinoma (1); dementia (1); endometrial cancer (1); head and neck cancer (1); kidney cancer (1); leukemia (1); lymphoma (1); neurodegenerative disease (1); pancreatic adenocarcinoma (1); prostate adenocarcinoma (1); rectal cancer (1); rectum adenocarcinoma (1); stomach adenocarcinoma (1); thyroid cancer (1); triple-negative breast carcinoma (1).